ADCY3 (adenylate cyclase 3)
Description:
Catalyzes the formation of the signaling molecule cAMP in response to G protein signaling. Participates in signaling cascades triggered by odorant receptors via its function in cAMP biosynthesis: specifically activated by G alpha protein GNAL/G(olf) in olfactory epithelium (By similarity). Mediates signaling cascades in primary cilia: specifically activated by G alpha protein GNAS/G(s) in primary cilia. Plays a role in regulating food intake and body fat accumulation in the paraventricular nucleus of the hypothalamus (PVH) by acting downstream of MC4R activation. Required for normal sperm motility and normal male fertility (By similarity).
Synonyms: AC-III; AC3; BMIQ19
Tractability: Small molecule: a high-quality ligand is known. Antibody: UniProt places it where antibodies can reach, with high confidence; its Gene Ontology location is reachable by antibodies, with high confidence; UniProt predicts a signal peptide or a membrane-spanning region. PROTAC: UniProt records ubiquitination sites on it; ubiquitination databases record sites on it; its protein half-life has been measured; a small molecule that binds it is known.
Target class: Enzyme; Lyase
Gene: Protein-coding gene on chromosome 2 (24,819,169 to 24,920,299, reverse strand). Ensembl gene ENSG00000138031.
Subcellular location: Cell membrane; Cell projection, cilium membrane; Cell projection, cilium; Cytoplasm; Golgi apparatus
Subcellular location (Human Protein Atlas): Nucleoplasm; Primary cilium; Basal body; Golgi apparatus; Nucleoli; Plasma membrane; Primary cilium transition zone
Pathways (Reactome):
Signal Transduction: Adenylate cyclase activating pathway; G alpha (i) signalling events; G alpha (s) signalling events; G alpha (z) signalling events; GPER1 signaling; Hedgehog 'off' state; PKA activation
Disease: ADORA2B mediated anti-inflammatory cytokines production; FCGR3A-mediated IL10 synthesis
Metabolism: Glucagon signaling in metabolic regulation; PKA activation in glucagon signalling
Cellular responses to stimuli: High laminar flow shear stress activates signaling by PIEZO1 and PECAM1:CDH5:KDR in endothelial cells
Neuronal System: Adenylate cyclase inhibitory pathway
Sensory Perception: Olfactory Signaling Pathway
Transport of small molecules: Vasopressin regulates renal water homeostasis via Aquaporins
Gene Ontology:
Molecular function: adenylate cyclase activity; phosphorus-oxygen lyase activity
Biological process: adenylate cyclase-activating G protein-coupled receptor signaling pathway; negative regulation of appetite; acrosome reaction; cAMP biosynthetic process; cellular response to forskolin; cellular response to glucagon stimulus; flagellated sperm motility; olfactory learning; renal water homeostasis; sensory perception of smell; single fertilization; vascular endothelial cell response to laminar fluid shear stress; cellular response to oxygen-containing compound; cyclic nucleotide biosynthetic process; intracellular signal transduction; system process
Cellular component: cytoplasm; membrane; non-motile cilium membrane; plasma membrane; ciliary membrane; cilium; cytoplasmic side of plasma membrane; Golgi apparatus
Genetic constraint (gnomAD): Loss-of-function variants: 67 observed, 118.08 expected, observed/expected ratio (o/e) 0.57, 90% interval 0.47 to 0.69. The upper end of that interval is the gene's LOEUF score, 0.69, which puts it in group 2 of 6, group 1 being the genes least tolerant of losing a copy. Missense variants: 1,236 observed, 1,584.3 expected, observed/expected ratio (o/e) 0.78, 90% interval 0.74 to 0.82. Synonymous variants: 672 observed, 644.27 expected, observed/expected ratio (o/e) 1.04, 90% interval 0.98 to 1.11.
Homologues: Orthologues: chimpanzee ADCY3 (99% identical), macaque ADCY3 (99% identical), rat Adcy3 (95% identical), mouse Adcy3 (95% identical), dog ADCY3 (94% identical), guinea pig ADCY3 (93% identical), pig ADCY3 (93% identical), rabbit ADCY3 (91% identical), tropical clawed frog adcy3 (78% identical), zebrafish adcy3a (76% identical), Drosophila melanogaster Ac3 (39% identical). Paralogues in human: ADCY5 (34% identical), ADCY6 (33% identical), ADCY8 (33% identical), ADCY7 (32% identical), ADCY2 (32% identical), ADCY1 (31% identical), ADCY4 (31% identical), ADCY9 (26% identical), GUCY2D (16% identical), GUCY2F (15% identical), NPR2 (14% identical), NPR1 (14% identical), and 5 more.
Diseases named in the same sentence as ADCY3 in open-access papers:
ADCY3 is named in the same sentence as 54 diseases in open-access papers, as found by Europe PMC text mining. Sharing a sentence is not in itself a finding about the gene and the disease. The quoted sentences say what the papers report.
Obesity (93 papers, 2009 to 2026). Accumulation of substantial excess body fat. "Here, we demonstrate that rs11676272, located in the ADCY3 gene, is a functional causal variant for obesity susceptibility." (PMID 41942711, 2026). "Three of the loci harbor genes implicated in severe and early-onset obesity – ADCY3, BDNF, and MC4R4." (PMID 40216759, 2025). "A study published in Nature Genetics reported a direct association between pathogenic variants in the ADCY3 gene and severe obesity in children from consanguineous Pakistani families, which further supports the significance of our identified variant." (PMID 40149731, 2025). "Dysfunction of this pathway, such as through ADCY3 loss‐of‐function mutations, has been associated with severe early onset obesity, hyperphagia, insulin resistance, and dyslipidemia." (PMID 41082226, 2025). "For instance, murine models with biallelic or monoallelic ADCY3 mutations have displayed increased susceptibility to obesity and insulin resistance." (PMID 40759647, 2025). "Together with our genetic and mechanistic data, this positions ADCY3 as a circadian-regulated metabolic effector that integrates genetic, behavioral, and environmental cues to influence obesity risk." (PMID 40766578, 2025). "The integration of consistent eQTLs and genetic associations of obesity GWAS validated the role of ADCY3, specifically in monocytes." (PMID 40759647, 2025). "ADCY3 is highly expressed in the brain, and rare, severe loss-of-function mutations were associated with monogenic obesity, highlighting its critical function in central energy homeostasis pathways." (PMID 40766578, 2025). "We provide evidence from large-scale human genetics and mechanistic mouse studies that a common missense variant in ADCY3, rs11676272, interacts with difficulty waking up to significantly increase an individual's risk of obesity." (PMID 40766578, 2025). "In humans, polymorphic variants at the ADCY3 locus are associated with increased BMI and fat mass, while carriers of loss-of-function alleles present with obesity, insulin resistance, dyslipidemia, and T2D." (PMID 41153348, 2025). "Recent findings point to a critical role of ADCY3 signaling in neuronal cilia, providing new mechanistic insight into obesity susceptibility." (PMID 41153348, 2025). "One of these variants, ADCY3 c.3380C>G, is involved in the development of obesity, while the other, KCNJ11 c.628A>G, is associated with type 2 diabetes and neonatal diabetes." (PMID 40149731, 2025). "Loss-of-function mutations in ADCY3 have been linked to obesity and T2D in humans and mice, whereas gain-of-function mutations are protective against diet-induced obesity." (PMID 41153348, 2025). "Rare ADCY3 mutations have been associated with impaired appetite control, contributing to early-onset severe obesity and insulin resistance." (PMID 39858569, 2024). "Adcy3−/− mice exhibit pronounced obesity, hyperphagia, and leptin resistance and lower physical activity, whereas the Adcy3 gain-of-function mutation results in reduced fat mass and body weights in HFD-fed mice." (PMID 39683011, 2024). "Mutations in several GPCRs, and notably those in the stimulatory G protein α subunit (Gαs) and specific adenylate cyclases, including ADCY3, are strongly linked to severe obesity." (PMID 39352389, 2024). "Genome-wide Association Studies (GWASs) found that the SNP of ADCY3 gene was associated with overweight/obesity in European, east Asians, and Chinese populations." (PMID 39060963, 2024). "Mutations in ADCY3 have been identified in children with severe monogenic obesity, while polygenic variants increase the risk of obesity and T2D, with the effect being more pronounced in homozygous carriers." (PMID 39858569, 2024). "Some studies suggested loss-of-function variants in ADCY3 increased the risk of obesity and type 2 diabetes." (PMID 39060963, 2024).
Obesity (continued). "Sequencing a customized gene panel of 52 obesity-related genes, we identified a novel homozygous nonsense variant, c.2520C>G p.Thr840X, in the ADCY3 gene." (PMID 39519366, 2024). "The association of the ADCY3 gene in the development of obesity has been emphasized by several studies from different populations." (PMID 39519366, 2024). "Taken together, these findings suggest that the nonsense variant leads to a loss of ADCY3 function, which in turn impairs enzymatic activity and contributes to the development of obesity, consistent with the patient’s phenotype." (PMID 39519366, 2024). "For example, the loss-of-function adenylate cyclase 3 (ADCY3) gene variant in Greenlanders is associated with lipogenesis, obesity, and T2DM due to impaired cAMP signaling in adipocytes." (PMID 39063184, 2024). "Homozygous loss-of-function variants in the ADCY3 gene lead to severe early-onset obesity and insulin resistance whereas gain-of-function variants protect against obesity." (PMID 39519366, 2024). "Several studies and meta-analyses based on Genome wide association study (GWAS) have shown that ADCY3 gene is associated with overweight/obesity and body mass index." (PMID 39060963, 2024). "Mutations in the ADCY3 gene have already been linked to obesity in mice and humans, making the gene a promising marker for obesity research in dogs." (PMID 37368776, 2023). "In GreenlandicEskimos, glucose homeostasis-related mutations in theTBC1D4 and ADCY3 genes have also been identified, whichincrease the risk of obesity and type 2 diabetes." (PMID 37465192, 2023). "ADCY3 knockout mice are obese, whereas ADCY3 gain of function mutation protects mice against obesity." (PMID 37329217, 2023). "Mutations in the ADCY3 gene have already been associated with obesity in mice and humans, making it a promising marker for canine obesity research." (PMID 37368776, 2023). "Our endeavour of unravelling genetic causality in SOPP also led to the identification of probands with these obesity syndromes and also uncovered that bi-allelic mutations in ADCY3 are a novel genetic cause of syndromic obesity." (PMID 37083980, 2023). "An Adcy3 knockdown in the VMH using Cre-recombinase methods produced hyperphagia-associated obesity in mice on a standard diet." (PMID 37064917, 2023). "For example, mutations of the ADCY3 gene cause obesity in children from consanguineous Pakistani families, while heterozygous mutations are associated with the severity of obesity in children of European–American descent." (PMID 36141228, 2022). "Further, Adcy3 loss-of-function variants are identified as a risk factor of obesity, which often co-occurs with depression." (PMID 36188604, 2022). "It has been reported that Adcy3 gene polymorphisms are associated with obesity and are known to be exclusively expressed in neuronal cilia." (PMID 34211092, 2021). "For instance, A gain of function of Adcy3 in mutagenized mice resistant to diet-induced obesity caused a reduction in both body weight, fat mass, insulin, and glucose levels compared to wild-type when subjected to high fat diet." (PMID 34177802, 2021). "The results revealed that 18 of the DMR genes were associated with addiction and obesity (ADCY3; ADCY9; ATF4; CDK5R1; CHRNB2; GABRD; GABRG3; GNB1; GNB3; GRK5; HDAC4; HDAC9; MAP2K1; PDE11A; PDE2A; PDE3A; PPP1CA; SLC6A3)." (PMID 34389046, 2021). "In obese participants, plasma ADCY3 levels and BMI were inversely correlated, which is in accordance with two recent population studies, identifying loss-of-function mutations within the ADCY3 gene are associated with severe obesity and T2D." (PMID 32847122, 2020). "The polymorphisms located in the regions of the POMC, DNAJC27 (RBJ), and ADCY3 genes were associated with pubertal development, height, BMI, obesity, and type I diabetes mellitus." (PMID 33552117, 2020).
Obesity (continued). "Nevertheless, genome-wide association studies have shown that ADCY3 polymorphisms (rs2033655 and rs1968482) are associated with obesity and other SNPs are involved in proximal gene regulation through changes in DNA methylation." (PMID 30926763, 2019). "In humans, different genetic variants located near or in the ADCY3 gene have been associated with obesity through candidate gene studies and genome-wide association studies (GWAS)." (PMID 29921800, 2018). "Among the ADCY3 genetic variants identified as related to obesity traits, the polymorphism rs10182181 has been replicated in the largest meta-analysis of GWAS on body mass index (BMI) carried out to date." (PMID 29921800, 2018). "Although ADCY3 has been associated with locomotor activity, food intake, and leptin sensitivity in mice, the exact mechanisms for its effect on obesity are unclear." (PMID 28763444, 2017). "For example, genetic association studies of the Adcy3 in Swedish12 and Chinese13 populations led to the discovery of Adcy3 polymorphisms associated with decreased risk of obesity." (PMID 27678003, 2016). "Additional genetic evidence supports an association between ADCY3 variation and obesity in both Swedish and Han Chinese populations." (PMID 25329148, 2014). "Animal models have also highlighted the importance of Adcy3 signaling in energy homeostasis, with Adcy3-/- mice having more fat mass under basal conditions and being more susceptible to obesity induced by high-fat feeding." (PMID 25329148, 2014). "Here we describe a novel allele of Adcy3, identified through forward genetic screening of mutagenized mice, which protects mice from diet-induced obesity." (PMID 25329148, 2014). "One of the obesity loci identified by GWAS maps at or near the ADCY3 gene, which encodes a member of the adenylate cyclase (AC) family of proteins." (PMID 25329148, 2014). "Importantly, although obesity-associated protein coding variants in Adcy3 have been identified in humans, with the exception of our previous work, no rodent models of protein-coding mutations in Adcy3 have been studied." (PMID 41542040, 2026). "In addition, biallelic loss-of-function mutations in ADCY3 have been associated with severe obesity, underscoring its involvement in regulating body weight and the development of obesity." (PMID 40759647, 2025). "We propose a unified model in which genetic variation in ADCY3 mediates the metabolic consequences of lifestyle and circadian strain, offering a functional framework that connects genetics, environment, and tissue-specific regulation to obesity risk." (PMID 40766578, 2025). "Several studies in humans also confirm the association of ADCY3 polymorphisms with obesity." (PMID 39519366, 2024). "In mice, Adcy3 deficiency leads to impaired insulin sensitivity and dyslipidemia, and studies in humans have found that loss-of-function variants in ADCY3 increase the risk for obesity and type 2 diabetes." (PMID 39329159, 2024). "Based on this profound thermogenic gene induction in Adcy3-at-deficient primary adipocytes, we hypothesized that loss of mAC3-AT might protect against obesity and obesity-induced metabolic alterations due to precocious BAT activation already under RT." (PMID 38684889, 2024). "A series of obesity-associated loci identified by genome-wide association studies (GWAS) are confirmed to be related to hypothalamic cilia, including adenylate cyclase 3 (ADCY3) and the melanocortin-4 receptor (MC4R)." (PMID 39126056, 2024). "Functional deficiencies in leptin and ADCY3 disrupt feeding control and promote obesity and T2D." (PMID 39352389, 2024). "The first model included genetic variants known to be associated with obesity—specifically, ADCY3 rs11676272, CLOCK rs1801260, GPR61 rs41279738, FTO rs1421085, RP11-775H9.2 rs1296328, SLC22A3 rs9364554, and TFAP2B rs734597—and explained 8.3% of the variance in BMI." (PMID 39766774, 2024).